TAP2 (transporter 2, ATP binding cassette subfamily B member)
Diseases named in the same sentence as TAP2 in open-access papers (continued):
Sharing a sentence is not in itself a finding about the gene and the disease.
tumor (88 papers, 2007 to 2026). "Some key molecules, such as CALR, HLA-A, HLA-DRB1, PDIA3, HLA-DQB1, HLA-E, and TAP2, have been implicated in various types of cancers and emphasized their important values related to the tumor progression." (PMID 31258820, 2019). "Loss of TAP1 and TAP2 further reduces tumour immunogenicity by limiting peptide loading onto MHC-I." (PMID 41179304, 2025). "We simultaneously analyzed the expression of TAP2 protein, IL-4 mRNA, CD11b mRNA and CK protein in tumor specimens from the NSCLC Cohorts #1 and #2." (PMID 40091029, 2025). "Using detailed spatial molecular analysis of human NSCLC cohorts and functional in vitro studies, we demonstrate the dominant effect of cancer cell TAP2 downregulation in tumor immune evasion and immunotherapy resistance." (PMID 40091029, 2025). "The immune escape from T cells caused by the knockout of genes IFN-γ signaling pathway (JAK1, JAK2, Ifngr2) and antigen presentation pathway (TAP1, TAP2, B2M) promotes tumor vulnerability to NK cells." (PMID 40191187, 2025). "In contrast, TAP2 downregulation prominently increased the viability of unstimulated A549 cells and almost totally prevented the tumor antigen-specific T-cell mediated killing induced by proinflammatory cytokines." (PMID 40091029, 2025). "The shRNA-mediated knockdown of LMP2 and TAP2 markedly enhanced the tumor size compared to the scramble group (P < 0.01)." (PMID 37986152, 2023). "We also observed that S1P treatment in tumor cells inhibited the expression of TAP2, CD27, CD160, and ICOSLG genes, which are important for the immune cell activation needed for antitumor responses." (PMID 35289120, 2022). "This means that, in combination with the previously reported expression of other antigen processing proteins such as TAP1 and TAP2, the essential components of the antigen presentation pathway are present in the tumor cells of HL." (PMID 33499248, 2021). "ENT treatment led to increased expression of ciita, tap1, tap2, cd74, and major histocompatibility genes—involved in antigen processing and presentation—suggesting an increased ability to T cells to engage tumor cells, consistent with previous reports." (PMID 33369199, 2021). "HPA001312 is an antibody against TAP2, which showed lower intensity in tumor tissue than in normal tissue." (PMID 33692827, 2021). "Fhit-transfected B11 tumor cells had increased transcriptional levels of the following genes: Fhit, H-2 class I heavy chains, β2-microglobulin, Tap-1, Tap2, LMP2, LMP10, Tapasin, calreticulin, Erap1, ERp57, PA28α, Ttp1, and Ttp2." (PMID 32545680, 2020). "Tumor associated antigens expressed by malignant cells are transported by TAP-1 and TAP-2 into the endoplasmic reticulum and loaded onto MHC-I, then translocate to the cell surface to present to CD8+ CTLs." (PMID 31737100, 2019). "Tap1, Tap2, and β2M genes were also upregulated, which are involved in natural killer cell recognition, and tumor cell processing of antigens and presentation through MHC I to cytotoxic CD8+ T cells." (PMID 30718505, 2019). "A decrease in TAP2, involved in peptide transport from the cytosol into the endoplasmic reticulum, was also observed specifically in the M5-T1 tumor." (PMID 29662647, 2018). "Conversely, the RMA/S tumor line, derived from RMA, harbors a nonsense mutation in Tap2, a key peptide transporter and regulator of MHC Class I surface expression." (PMID 29892299, 2018). "Results indicated that 53% and 32% of the tumours displayed low and intermediate expression levels of TAP2, respectively, while only 14% of human lung tumours expressed high levels of the TAP2 subunit." (PMID 30504837, 2018). "There are several studies on the relationship between TAP (including TAP1 and TAP2) polymorphisms and various carcinoma, and only TAP1 polymorphisms have been confirmed to be susceptible to various tumor types." (PMID 26205887, 2015).
tumor (continued). "Consistent with the microarray transcript data, immunohistochemical staining confirmed increased expression of HLA-DR, CD74, and TAP2 proteins in the tumor epithelium of the low-volume ascites group." (PMID 24982872, 2014). "The loss or dysfunction of molecules involved in antigen processing and presentation (such as TAP1, TAP2, LMP2, LMP7 and Tapasin) via the class I pathway contributes to deficient class I expression in several tumor types." (PMID 24212778, 2011). "It has been shown that HDACi treatment can activate the proteasomal components (LMP2, LMP7), transporters associated with antigen processing (TAP1, TAP2) and the TAP-associated glycoprotein (tapasin) gene in tumor cells." (PMID 24212778, 2011). "One such T-cell clone recognizes an ER-localized-Lass5-protein-derived antigen that is presented exclusively by RMA-S and other TAP1 or TAP2 deficient cells and protects mice from RMA-S tumor challenge." (PMID 19629186, 2009). "We hypothesized that accumulation of immune suppressive cytokines in the tumor microenvironment could participate in the epigenetic TAP2 silencing on malignant cells." (PMID 40091029, 2025). "The possible contribution of TAP2 increase in their anti-tumor mechanism of action could explain, at least partially, the marked immunostimulatory effect of some of these treatments." (PMID 40091029, 2025). "However, a subset of cases showed marked reduction of TAP1 and/or TAP2 only in cancer cells (CK+) with preservation of the signal in the neighboring non-tumor lung tissue and/or stromal cells (CK-) supporting cancer cell selective protein downregulation." (PMID 40091029, 2025). "Similarly, the expression of genes related to antigen processing and presentation such as Tap1, Tap2, B2m, and Psmb9, was also upregulated in tumors from hsBCL9z96-treated CT26 tumor-bearing mice and MC38 tumor-bearing Bcl9/Bcl9l deficiency mice." (PMID 38811552, 2024). "In vivo studies substantiated that LMP2 and TAP2 antagonized tumor growth." (PMID 37986152, 2023). "Additionally, analysis of bulk tumor RNA demonstrated an increase in antigen presentation (H2-Q2 and H2-Eb1) and antigen transport (Tap2) related genes within Kin1-NULL tumors." (PMID 36883731, 2023). "TAP2, another SMR gene, localises to the MHC class II region and plays a pivotal role in immune surveillance, with polymorphisms linked to the susceptibility of various autoimmune disorders and various neoplasms." (PMID 33549134, 2021). "Whereas levels of TAP2 were almost unchanged in the 21 tumor-free samples studied here, the group with TAP1 mRNA levels below the median showed significantly better overall and disease-free survival when considering age, sex, cytolytic activity, and tumor stage." (PMID 32867395, 2020). "Presentation of tumor associated antigens by MHC-I molecule is regulated by the transcription of antigen processing machinery (APM) genes involving low molecular mass proteins LMP-2 and LMP-7 and transporters associated with antigen processing TAP-1 and TAP-2." (PMID 31737100, 2019). "Restoration of the expression of TAP2 may increase tumor-specific immune responses and survival." (PMID 35603163, 2022). "A reduction in TAP2 expression results in the reduced stability and expression of MHC molecules on the tumor cell surface, in turn leading to immune evasion by tumor cells." (PMID 40141198, 2025). "SAHA also significantly upregulates the expression of four antigen presentation-related proteins—TAP1, TAP2, LMP2, and LMP7—in U251 and GL261 cells, enhancing immune cell recognition of tumor cells." (PMID 40573881, 2025). "In parallel, CAF-derived TGF-β suppresses antigen-processing genes (e.g., TAP2, ERAP1, β2-microglobulin) via Smad3, reducing MHC-I surface expression and dampening tumor immunogenicity." (PMID 41228299, 2025). "With the help of TAP1 and TAP2, CD8+ T cell can identify MHC-I molecules on the exterior of tumor cells, resulting in the destruction of tumor cells." (PMID 39132149, 2024).
tumor (continued). "TAP1, TAP2, TAPBP, and β2-microglobulin (B2M) are critical proteins involved in the class I MHC antigen presentation process in virus-infected or tumor cells." (PMID 39388288, 2024). "Knockout of TRIM21 resulted in high expression of HLA-A, B2M, TAP1 and TAP2 in SUNE1 tumour cells isolated from BALB/c nude mice and of B2m, Tap1, Tap2, Tapbp and Earp1 in MC38 tumour cells isolated from C57BL/6 mice." (PMID 36797289, 2023). "The increased tumor growth resulting from LMP2 and/or TAP2 depletion was also partially reversed by suppressing Wnt1 levels." (PMID 37986152, 2023). "STING agonists are verified to induce tumor cells apoptosis, allowing the leak of antigen-presenting molecules such as TAP1, TAP2, and MHC-I via the upregulation of IFN to further cross-prime anti-tumor T-cells and enhance immunosurveillance of tumors." (PMID 37122745, 2023). "Most MHC I molecules, including HLA-A, HLA-C, HLA-E, HLA-F, TAP1, TAP2, and TAPBP (all P < 0.05), were upregulated in PTPRD/PTPRT mutant patients, indicating enhanced anti-tumor immunity in PTPRD/PTPRT mutant patients." (PMID 36248841, 2022). "In order to determine the expression levels of HLA-I/APM components in OSCC, protein expression of HLA-I HC, β2-m and the APM molecules TAP1, TAP2, LMP2 and LMP10 were analyzed by IHC of formalin-fixed, paraffin-embedded (FFPE) tumor lesions." (PMID 33557271, 2021). "Further, we analyzed IRF8 target gene expression in GMPs, MDPs, and CDPs and found that, relative to controls, tumor-bearing mice had decreased mRNA expression of multiple MHC molecules, as well as TapBP, Tap2, Batf3, and Pml." (PMID 29593283, 2018). "Our analysis also revealed modest expression of the HLA genes, including low expression of peptide transporters TAP1 and TAP2, in the LS-CRC tumour." (PMID 30108227, 2018). "To estimate the percentage of tumours with TAP protein defects, we performed IHC staining with anti-TAP2 mAb in a cohort of 135 FFPE lung tumour samples." (PMID 30504837, 2018). "A number of other immune genes, including MHC class I, components of the class I peptide presentation pathway (TAP1, TAP2, LMP2, LMP7 and Tapasin), B7-1/2, NKG2D ligands and certain tumor antigens, are also silenced by chromatin in multiple tumor types." (PMID 18070359, 2007). "Analysis of tumors from ApcMin/+/Ptpn13fl/fl/Vil-CreERT2 (APV) mice showed that Ptpn13 knockout, induced by TAM treatment, significantly upregulated the expression of IRF1, LMP2, TAP1, TAP2, H2-D1, H2-K1, and B2M and also increased the surface levels of MHC-I complex on tumor cells." (PMID 41486293, 2026). "While GBM tumours frequently exploit immune evasion mechanisms such as PD-L1 overexpression, MHC-I downregulation, and impaired antigen presentation via TAP1/TAP2 suppression, translation of these findings into effective immune checkpoint inhibitor (ICI) therapies has proven challenging." (PMID 41179304, 2025). "Using multiplexed immunofluorescence, we spatially mapped CD8+ effector Tumor-Infiltrating Lymphocytes (TILs) and the APM components TAP1 and TAP2 in 819 baseline/pre-treatment NSCLCs from patients treated with and without PD-1 axis blockers in 4 independent cohorts." (PMID 40091029, 2025). "In contrast, ENHO exhibited negative co-expression with MHC class I-related genes (TAP1, TAP2, and TAPBP), which may reflect a tumor-driven mechanism aimed at evading cytotoxic T cell-mediated immune surveillance." (PMID 40647442, 2025). "We next tested the association of primary/metastasis-specific downregulation of an MHC class I metagene signature composed of a composite expression of HLA-A, HLA-B, HLA-C, B2M, TAP1, TAP2 and NLRC5 between metastasis and matched primary tumor according to intrinsic subtype." (PMID 36585450, 2023).
tumor (continued). "To simulate the immune evasion mechanism of HLA-I downregulation in tumor cells in vitro, we first knocked out TAP1 and TAP2 simultaneously and knocked out B2M genes in several solid tumor cells (A375, A549 and 786-O) using CRISPR/Cas9 technology, respectively." (PMID 36612246, 2022). "Subsequently, we analyzed SQLE expression and its association with biomarkers of MHC (B2M, HLA-B, HLA-C, TAP1, and TAP2), dendritic cells (BATF3), macrophages (CD68 and IL1A), type-I anti-tumor responses (CD8A and GZMB), and cell proliferation (MKI67) in 178 PAAD tissues." (PMID 35720314, 2022). "The expression levels of B2M(p = 2.926e-05), HLA-C(p = 2.628e-03), HLA-E(p = 5.5166e-08), HLA-F(p = 9.376e-03), TAP1(p = 1.972e-09), TAP2(p = 1.245e-04) and TAPBP (p = 2.652e-12)in tumor tissues of dMMR patients were significantly higher than those of pMMR patients." (PMID 36527024, 2022). "TAP2 (P < 0.001; Cor = 0.60), PSME2 (P < 0.001; Cor = 0.52), HLA - E (P < 0.001; Cor = 0.69), and LCK (P < 0.001; Cor = 0.69) positively related to CD8+ T cell and negatively correlated with tumor purity." (PMID 33692827, 2021). "A previous study reported the functional significance of TAP1 (but not TAP2) expression in tumour cells." (PMID 33128234, 2020). "Also correlating were GZMB and FASLG, both necessary for anti-tumor CD8 T cell cytotoxic functionality, PD-1 and LAG3, representing T cell activation and exhaustion, and TAP2, necessary in MHC I antigen presentation." (PMID 29487705, 2018). "The tumor specimens represented in the TMAs expressed the TAP1 and TAP2 subunits at various levels." (PMID 29091951, 2017). "Importantly, we demonstrated that by inducing re-expression of TAP-2 in OE19 with INF-γ treatment or by incubating the cells with INF-γ producing CTLs, the specific anti HER-2 CTL tumor lysis response and synergistic effect with trastuzumab can be restored." (PMID 20865050, 2010). "Once these CTLs invade the tumor environment and target the tumor cells, INF-γ release could re-establish TAP-2 expression." (PMID 20865050, 2010). "In particular, B7.1 transfected TAP1-expressing RMA-S cells can elicit T-cell clones reacting with TAP1 or TAP2 deficient tumor cells, but not with TAP-competent tumor cells." (PMID 19629186, 2009). "In addition, the screen included as a second parameter the changes in PD-L1 protein levels, with the goal of selecting agents able to restore TAP2 without increasing PD-L1 mediated tumor immune evasion." (PMID 40091029, 2025). "Additionally, upregulated antigen-presenting machinery comprising TAP1, TAP2, and MICB suggested that the cytotoxic T cells could be selectively programmed against tumor cells." (PMID 35884843, 2022). "In each tumor cell line, exposure to radiation significantly increased the expression of ≥ 6 APM components by ≥ 30%, namely the immunoproteosome subunits LMP2, LMP7, and LMP10; the peptide transporters TAP1 and TAP2; and the chaperones calnexin (2/3 cell lines) and tapasin (3/3 cell lines)." (PMID 24480782, 2014). "Genes of the antigen-processing machinery and regulation (IRF1, IRF2, NF-κB1, NF-κB2, NLRC5, TAP1, TAP2, TAPBP) were not significantly expressed throughout all of the analyzed tumor transcriptomes." (PMID 35892842, 2022). "Presence of somatic variants in genes related to antigen presentation, including HLA-A, HLA-B, HLA-C, B2M (β-2-microglobulin), TAP2, and PSMB8 (LMP-7), did not predict tumor classification." (PMID 30824826, 2019). "Similarly, the expression of TAP2, TAPBP, PSMB8, and B2M was each shown to be induced by VC treatment in the WT, but not TET2-KO, tumor cells." (PMID 39388288, 2024).
cancer (43 papers, 2007 to 2025). A tumor composed of atypical neoplastic, often pleomorphic cells that invade other tissues. "Cancer cell TAP2 protein downregulation was spatially associated with high local IL-4 mRNA expression." (PMID 40091029, 2025). "Consistent with our results, previous studies have also shown that the alterations in TAP1 and TAP2 proteins in cancer cells are uncommonly associated with deleterious genomic alterations and were suggested to occur as a consequence of protein dysregulation." (PMID 40091029, 2025). "An oncoprint plot showed genomic alterations in genes encoding the HLA-I, B2M, TAP1 and TAP2 that would influence antigen presentation, amounting to ~12% of 10,967 cancer patients in the TCGA data set." (PMID 36612246, 2022). "Many investigations in the literature have demonstrated loss of TAP1 and TAP2 expression in human cancers." (PMID 29091951, 2017). "However, low cancer cell TAP2 expression was associated with a significantly shorter OS and 82% increased risk of death only in patients treated with PD-1 axis blockers (Cohort #4; HR 1.82 [CI: 1.12–2.96])." (PMID 40091029, 2025). "To assess the impact of TAP2 loss on surface HLA-peptide complexes stabilization and tumor antigen-specific cancer cell killing, we performed peptide re-loading experiments by exposing parental or TAP2-deficient A549 cells to purified HER2369-377 or MAGE3271-279 peptides." (PMID 40091029, 2025). "We identify a previously unrecognized multi-step mechanism by which cancer cell TAP2 downregulation mediates adaptive immune escape." (PMID 40091029, 2025). "Quantification of the markers within specific cell type compartments revealed higher IL-4 mRNA expression in intratumor myeloid cells than in cancer cells, as well as lower TAP2 protein levels in cases with high myeloid cell IL-4 mRNA expression." (PMID 40091029, 2025). "We also identify local IL-4 produced by intratumor myeloid cells as a critical factor inducing TAP2 downregulation in cancer cells and mediating reduced sensitivity to PD-1 axis blockers." (PMID 40091029, 2025). "We identified cancer cell selective TAP2 protein downregulation in 42.4% of treatment naïve NSCLCs associated with reduced sensitivity to immune checkpoint blockers." (PMID 40091029, 2025). "The spatially resolved analysis by QIF revealed that ~ 42.4% of 819 immunotherapy naive primary NSCLCs from multiple independent cohorts, and including early stage/resectable tumors, show cancer cell selective downregulation of TAP2 protein." (PMID 40091029, 2025). "Similar results were obtained using PC9 cells as T-cell targets, as well as in A549 cells with TAP2 gene elimination, in which the cancer cell survival increase was suppressed by the re-introduction of TAP2." (PMID 40091029, 2025). "Our results identify cancer cell selective TAP2 downregulation as a dominant, reversible, and potentially actionable mechanism of adaptive immune evasion and immunotherapy resistance in NSCLC." (PMID 40091029, 2025). "Here, the intratumoral expression of TAP1 and TAP2 showed higher clustering with increasing M1 population in several cancer types." (PMID 34078917, 2021). "CD74, HLA-DR, and TAP2 were expressed at significantly higher levels in the epithelium of cancer cells derived from tumors of patients with low- versus high-volume ascites (P = 0.046, P = 0.006, and P = 0.002, resp)." (PMID 24982872, 2014). "HLA-HC, β2 microglobulin, tapasin, TAP-1, and TAP-2 were detected on cell membranes and cytoplasm in both cancer cells and normal mucosa." (PMID 22134332, 2012). "Together, these results suggest that TAP2 downregulation in cancer cells could be more energy-efficient and produce a deeper immune evasion than TAP1 reduction." (PMID 40091029, 2025).